CGAS (cyclic GMP-AMP synthase)
Diseases named in the same sentence as CGAS in open-access papers (continued):
Sharing a sentence is not in itself a finding about the gene and the disease.
infection (continued). "Strikingly, the capsid inhibitor lenacapavir also disrupted viral cores and dramatically potentiated cGAS activity, both in vitro and in cellular infections." (PMID 39874383, 2025). "The mRNA transcription level of cGAS was also detected after infection with G. parasuis or OMVs for 16 h." (PMID 40597313, 2025). "Within the pathophysiological framework of NAFLD, the cGAS-STING pathway transitions from its traditional role as an antagonist to infection to become a pivotal mediator of sterile inflammation." (PMID 41041344, 2025). "This signaling consists of the enzyme cGAS and the transmembrane protein STING, which together function to recognize cytosolic double-stranded DNA (dsDNA), a hallmark of cellular stress or infection." (PMID 41438738, 2025). "We then focused on the cGAS–STING pathway showing that it is induced by infection of astrocytes and microglia, and its inhibition partially rescues the electrical activity dampened by SARS-CoV-2 in rat cortical cells." (PMID 41139159, 2025). "The cGAS/STING pathway can efficiently recognise HCMV DNA during productive infection of differentiated cells like fibroblasts and dendritic cells, triggering antiviral type I IFN responses." (PMID 40872823, 2025). "Cytosolic DNA, originating either from infections, endogenously through phagocytosis, or released from mitochondria, initiates the production of 2′3′-cGAMP (cG[2′–5′]pA[3′–5′]p) via the enzyme cGAS." (PMID 40981440, 2025). "The cGAS-STING pathway has emerged as a central mediator of inflammation in infection, cellular stress, and tissue injury." (PMID 40335920, 2025). "Since it has been shown that during infection with IAV the cGAS-STING pathway is being activated due to release of mitochondrial DNA (mtDNA), we analyzed the genes of the KEGG cytosolic DNA sensing pathway." (PMID 39543713, 2024). "Subsequently, qPCR was used to quantify the binding affinity of cGAS to cytosolic mtDNA under SFTSV infection." (PMID 38712963, 2024). "Research findings already show that combining D-GalN with LPS to create an ALI model triggers the activation of the cGAS-STING signaling pathway and During ALI, the organism's cellular damage or infection also triggers the activation of the cGAS-STING pathway." (PMID 39148120, 2024). "The cGAS-STING pathway is efficiently activated during NH/P68 attenuated strain infection, producing large amounts of IFN-β to inhibit ASFV replication." (PMID 38426093, 2024). "For example, during Staphylococcus aureus skin infection, TLR and cGAS/STING signaling pathway activation regulates the expression of approximately 95% of genes in macrophages within the first four hours of infection." (PMID 38339107, 2024). "Innate nucleic sensing pathways such as cGAS-STING monitor pathogenic and aberrant DNAs to guard against pathogen infection and maintain tissue homeostasis." (PMID 39304793, 2024). "cGAS (cyclic GMP-AMP synthase) senses cytosolic DNA originating from pathogen infection or genome instability." (PMID 39186813, 2024). "The cGAS–STING pathway has emerged as a key mediator of inflammation during infection, cellular stress and tissue damage." (PMID 39044275, 2024). "cGAS is an important abnormal state receptor that can recognize and bind to abnormal double-stranded DNA produced by pathogen infection or cellular stress, leading to the synthesis of 2',3'-cGAMP." (PMID 39148120, 2024). "ZIKV, an RNA virus, has been reported to promote NLRP3 inflammasome activation to benefit its infection by stabilizing caspase-1 to suppress cGAS-mediated type I IFN signalling." (PMID 38426093, 2024). "Our data indicate that infection with the isoniazid-resistant M. tuberculosis strain preferentially resulted in cGAS-STING/STAT1 activation, which induced a characteristic host immune response." (PMID 39597535, 2024). "Combining these findings, our data suggest an activation of the cGAS-STING pathway in hMdM after infection with IAV due to the release of mtDNA." (PMID 39543713, 2024).
infection (continued). "In contrast, in cGAS-STING pathway-deficient cells, the impaired immune response induced by PRUΔROP5 infection was restored." (PMID 39457045, 2024). "Macrophages are more likely to exhibit cellular senescence, impaired mitochondria, and abnormal activation of the cGAS-STING and NLRP3 inflammasome pathways, which predispose mice to severe viral pneumonia during infection." (PMID 38195584, 2024). "When there is an infection, cellular damage, or tissue injury, the cGAS-STING signaling pathway becomes an essential link in inflammation." (PMID 38481801, 2024). "KSHV blocks multiple immune pathways to maintain its lifelong infection, one of which is the DNA-sensing cGAS-STING pathway." (PMID 38464154, 2024). "KSHV blocks multiple immune pathways to maintain its persistent infection, one of which is the DNA-sensing cGAS-STING pathway." (PMID 39186813, 2024). "THP1 monocytes with CRISPR-mediated knockout of either STING or cGAS accumulated fewer IFNB1 transcripts compared to wild-type cells following infection with HCMV AD169." (PMID 38932169, 2024). "The cGAS/STING pathway triggers inflammation upon diverse cellular stresses such as infection, cellular damage, aging, and diseases." (PMID 38177926, 2024). "Interference with SPSB3-regulated nuclear cGAS degradation primes cells for type I interferon signalling, conferring heightened protection against infection by DNA viruses." (PMID 38418882, 2024). "The concentration of cGAS was significantly increased 24 h p.i., and there was a significant increase of cGAMP in aged hMdM 8 h and 24 h after infection with IAV/PR8." (PMID 39543713, 2024). "Decreased cGAS/STING signaling increases the severity of these infections as several pathogens have evolved different mechanisms to evade this system along with other PRRs." (PMID 38339107, 2024). "We also observed that ECTV.ΔvSlfn infection was sufficient to result in detectable activation of STING and IRF3, and this was abolished in cells deficient for cGAS or STING." (PMID 39431915, 2024). "Various studies have demonstrated that infection with either DNA or RNA viruses triggers mtDNA release from mitochondria into the cytosol, where it activates the cGAS-MITA/STING axis, leading to the activation of downstream antiviral effectors." (PMID 37932533, 2023). "Blocking mtDNA release by VBIT-4, a VDAC50 inhibitor, suppressed EV-A71 infection induced cGAS-STING activation." (PMID 36823147, 2023). "The cGAS-STING pathway plays a critical role in the innate immune response to infection of a variety of DNA pathogens through the induction of the type I interferons." (PMID 36575042, 2023). "It has been established that infection of murine macrophages with F. novicida leads to the induction of IFN-β in a cGAS-STING-dependent manner, which subsequently binds to interferon-alpha/beta receptor in an autocrine fashion." (PMID 37266012, 2023). "Through cytosolic DNA sensing, the cyclic GMP-AMP synthase-stimulator of interferon genes (cGAS-STING) pathway acts as a key mediator of inflammation in response to infection, cellular stress and tissue damage." (PMID 37217935, 2023). "Among all of the vaccinia-encoded cGAS inhibitor candidates identified in this study, E5, K7, C11, WR199/B18, and WR200/B19, and previously reported B2 (poxin), only VACV∆E5R infection of BMDCs induced significant levels of type I IFN." (PMID 37217469, 2023). "Upon infections, increased amounts of foreign intracellular DNA are sensed by cGAS, which belongs to the nucleotidyltransferase (NTase) enzyme family." (PMID 36825026, 2023). "Both monoubiquitinated and polyubiquitinated cGAS bands were detected as early as 2 h post-infection and increased at 4 and 6 h post-infection." (PMID 37217469, 2023). "IFN-β and ISG54 mRNA expression, as well as the IFN-β protein expression were significantly decreased in cGAS-/- cells compared to WT cells during SVV or EV-A71 infection." (PMID 36745686, 2023).
infection (continued). "Here we show that MVA infection induces mono-and poly-ubiquitination of cGAS and promotes its degradation in a proteasome-dependent manner." (PMID 37217469, 2023). "More specifically, after infection with T. gondii, the T. gondii genome undergoes rapid replication in the cytosol of cerebral cells, activating cGAS." (PMID 37686127, 2023). "The cGAS-STING-TBK1-IRF3 pathway can protect against pathogen infection and mediate the inflammation on the condition of cell stress and tissue damage, whose activation is closely associated with autoinflammatory and degenerative diseases." (PMID 37122745, 2023). "We also demonstrated a pro-viral role for immunosuppressive BAF activity in uninfected cells in promoting primary infection with KSHV through its impact on cGAS." (PMID 36746947, 2023). "Combined, these findings suggest that B2 and F17 function at different times and in different ways to counteract different functions of cGAS activation over the course of infection." (PMID 38036506, 2023). "Although HSV is a DNA virus, its infection can also stimulate the liberation of mtDNA and activate the cGAS-STING pathway." (PMID 37065192, 2023). "Of note, it is demonstrated that the release of mitochondrial DNA to cytosol is observed during infection with dengue virus, one of Flaviviruses, resulting the activation of cGAS." (PMID 36703213, 2023). "cGAS not only identifies free abnormal DNA in the cytoplasm, but is also involved in the infection process of RNA viruses." (PMID 37515271, 2023). "When SLK cells were treated with BANF1 or NTC siRNA prior to infection with rKSHV.219, the cGAS expression of BANF1 siRNA transfected cells was increased compared to NTC." (PMID 36746947, 2023). "Second, such rapid cGAS degradation has not been reported previously and by contrast, we only observe partial destabilization of cGAS at later stages of infection by WT VacV." (PMID 38036506, 2023). "Considering that diet and metabolism can regulate immunity to control infection morbidity and mortality,[8a,b] we examined the role of FA in cGAS activation by herpes simplex virus‐1 (HSV)." (PMID 36950761, 2023). "We show that in conditions of TBK1 deficiency, IKKε induction is crucial to ensure unmitigated type I IFN responses after specific activation of cGAS and RLRs, and also during infection with Listeria monocytogenes." (PMID 36936901, 2023). "This suggests that the cGAS-STING axis can significantly reduce RNA virus production in bat cells during infection." (PMID 37744905, 2023). "As a result, it can be difficult to tell if these events are driven by infection to counter a specific cGAS-mediated antiviral response or occur as part of infection-induced apoptotic processes." (PMID 38036506, 2023). "In line with our in vitro study, we found that cGAS functions as a DNA sensor in pDCs for detecting YM gDNA at the early infection stage and primarily induces STING-mediated type I IFN signaling." (PMID 36825026, 2023). "During infection, the presence of foreign DNA in the cytosol leads to activation of cGAS and subsequent induction of the IFN-I response." (PMID 36882786, 2023). "CCF, the outcome of pathogen infection and senescence, is recognized by cGAS, and activation of cGAS promotes the production of SASP factors through activating STING." (PMID 37543653, 2023). "Lung CFU were significantly increased in cGAS KO mice at 14 days after intratracheal infection as compared to WT controls." (PMID 37261352, 2023). "When neutrophils are engulfed by macrophages as a mechanism of resolution of an infection, NETs translocate to the cytoplasm of macrophages, where they trigger cGAS/STING signalling activation." (PMID 37077526, 2023). "PCV2 is a type of PCV that promotes cyclic GMP-AMP synthase (cGAS) phosphorylation at S278 in the early stages of infection by activating phosphatidylinositol 3-kinase (PI3K)/Akt signaling, which directly silences cGAS catalytic activity." (PMID 37638049, 2023).
infection (continued). "Infection by Zika virus (ZIKV), measles virus (MeV), or severe acute respiratory syndrome coronavirus 2 (SARS-CoV-2) also causes mtDNA release and cGAS–STING signaling." (PMID 37001140, 2023). "PRRSV, as an RNA virus, has also been reported to have the cGAS-STING signaling pathway involved in its infection process." (PMID 37515271, 2023). "It has been established that infection with RNA viruses is mainly sensed by RIG-I and MDA5, while infection with DNA viruses is mostly sensed by cGAS." (PMID 37932533, 2023). "Taken together, it appears that GoraVir induces cell-type specific ISG responses upon infection which seem, at least in part, to be dependent on a functional cGAS/STING pathway." (PMID 36851497, 2023). "The induction of IFN-I depends on the cGAS-STING pathway as cGAS- and STING-deficient mice are more susceptible to HSV-1 encephalitis after peripheral infection." (PMID 37941028, 2023). "CHIKV suppresses IFNβ expression by inducing the autophagy-dependent degradation of cGAS as early as 4 h post infection." (PMID 37077526, 2023). "Highlighting its essential role in preventing cellular infection and replication, many DNA and RNA viruses have co-evolved mechanism to antagonize the cGAS–STING pathway." (PMID 37247757, 2023). "We next examined the impact of F. tularensis LVS infection on the cGAS-STING pathway upstream of Aim2 by determining the levels of IFN-β in wild-type, Aim2−/−, Sting−/− and immortalized Gsdmd−/− BMDMs." (PMID 37266012, 2023). "Of note, kynurenine levels were elevated in the sibling not on allopurinol, which is relevant in that this tryptophan metabolite is elevated in response to cGAS-STING-interferon activation secondary to infections (e.g., SARS-CoV-2)." (PMID 37760001, 2023). "As for pro-inflammatory activity, cyclic GMP-AMP synthase (cGAS) detects infections by binding to cytosolic DNA from bacteria or viruses." (PMID 35846745, 2022). "We thus concluded that ΔM062R infection stimulated a unique pro-inflammatory state that is cGAS-dependent and also regulated by SAMD9." (PMID 36103568, 2022). "Intriguingly, in the cytosol, co-localization of cGAS with micronucleus-like bodies whose presence increased with infection progression was observed." (PMID 35458396, 2022). "The stimulator of interferon genes (STING) is a critical molecule that binds to the cyclic dinucleotides (CDNs) generated by the cyclic GMP-AMP synthase (cGAS) to initiate the innate immune response against infection." (PMID 36297353, 2022). "cGAS primarily detects invading pathogenic DNA, therefore, leaked dsDNA from mitochondrial during cell damage or infection can be sensed by cGAS to evoke necessary type-I interferons and inflammatory cytokines production." (PMID 39871923, 2022). "When WT- and E1A-deleted adenoviruses have been used for the infection of human HeLa cells, the cGAS–STING pathway activation levels were comparable at least up to 6 h post infection." (PMID 35458396, 2022). "Their findings revealed an indispensable role of RNF111-mediated neddylation modification for cGAS activation and cGAS-mediated restriction of DNA pathogens infection." (PMID 36042206, 2022). "NS2B targets cGAS for lysosomal degradation, which helps to avoid the detection of mitochondrial DNA by cGAS during infection and results in type I IFN response inhibition in primary human monocyte-derived dendritic cells." (PMID 36016430, 2022). "Cellular infection with HSV-1 releases cGAS from the chromatin into the nuclear soluble fraction, leading to viral sensing and a type I interferon host response." (PMID 35538147, 2022). "The presence of cytosolic DNA during infection activates the cyclic GMP-AMP synthase (cGAS) and stimulator of IFN genes (STING) signaling pathway, which is critical for limiting the replication of viruses." (PMID 36419185, 2022).
infection (continued). "While we confirmed the activation of the cGAS pathway by ΔM062R, we also confirmed our earlier observation that ΔM062R infection led to apparent upregulation of ISGs in comparison to wildtype MYXV infection." (PMID 36103568, 2022). "Together, physical interactions between cGAS and S. Typhimurium DNA have been identified in the context of infection." (PMID 35604097, 2022). "In the late stage of infection, however, continuously activated cGAS results in a constantly increased cGAMP concentration." (PMID 35803579, 2022). "As a DNA virus, PRV can establish long-term infection by evading cGAS-STING- and TLR3-induced antiviral innate immune responses." (PMID 35891444, 2022). "Herein, we assessed the effect of kDNA on parasite loads in in vitro infection models and evaluated the role of cGAS-STING-TBK1 DNA-sensing pathway in the context of L. major infection." (PMID 36405710, 2022). "Immunogenic modified MVA infection of DCs can induce type I IFN by activating the cyclic GMP-AMP synthase (cGAS) and stimulator of IFN gene–mediated (STING-mediated) cytosolic DNA–sensing pathways." (PMID 35852856, 2022). "Infection with two HSV-1 strains, McKrae and KOS caused a portion of cGAS to translocate to the nuclear soluble fraction." (PMID 35538147, 2022). "We found that the replication-defective ΔM062R activated host DNA sensing pathway during infection in a cGAS-dependent fashion and that knocking down SAMD9 expression attenuated proinflammatory responses." (PMID 36103568, 2022). "This revealed that caspase activity specifically inhibits cGAS to impede IFN signaling during KSHV lytic infection." (PMID 36255240, 2022). "Accumulating evidence suggests the cytosolic DNA-sensing pathway cGAS-STING plays an important role in inducing type I IFN response during intracellular bacterial pathogen infection (13, 19, 37, 43, –, 46)." (PMID 35604097, 2022). "Both DNA and RNA viruses have evolved mechanisms to suppress or evade the cGAS-STING pathway to allow for successful infection." (PMID 35877778, 2022). "In skin-scarification-infection-model studies in mice, the ΔB2R virus replicated to levels ~40 times lower than the parental WR strain, suggesting that the cGAS/STING pathway significantly contributes to poxvirus restriction during infection of the skin." (PMID 36145493, 2022). "By contrast, MVA infection induces IFN production via the cGAS/STING-mediated cytosolic DNA-sensing pathway." (PMID 36261460, 2022). "The results showed that the deficiency of Cgas markedly reduced the Ifnb1 transcripts in the liver and IFNβ in the blood at both time points post infection, indicating that cGAS is important for the induction of IFNβ during S. japonicum infection." (PMID 35108342, 2022). "To clarify the function of cGAS in the process of S. japonicum infection, we employed an acute infection model by infecting mice with schistosome cercariae." (PMID 35108342, 2022). "When cytosolic DNA is present, such as in the setting of infection, cGAS binds to dsDNA to create a 2:2 complex." (PMID 35693769, 2022). "ZIKV NS1 also, through complex mechanism, promotes cleavage of cGAS, which decreases recognition of DNA during infection and inhibits type I IFN." (PMID 36016430, 2022). "When infection, stress, or cell damage occurs, cGAS recognizes pathogens in the cytoplasm, and uses ATP and GTP to produce the second messenger cyclic GMP-AMP (cGAMP)." (PMID 35280696, 2022). "The KO(LL/RK-NLS) RAW264.7 cells were treated with DMSO or the cGAS inhibitor RU.521 followed by HSV-1 KOS d109 infection." (PMID 35538147, 2022). "DENV NS2B protease cofactor targets the cGAS for lysosomal degradation to avoid the detection of mtDNA during infection." (PMID 35558078, 2022). "Virus and cGAS are always in a state of mutual antagonism, but how PRRSV antagonizes the antiviral effect of cGAS in natural infection remains to be further studied." (PMID 35558078, 2022).